IL6 (interleukin 6)
Diseases named in the same sentence as IL6 in open-access papers (continued):
Sharing a sentence is not in itself a finding about the gene and the disease.
depression (continued). "Data from population-based studies suggest that elevated levels of circulating IL-6 and CRP are associated with particular symptoms of depression, such as fatigue, sleep and appetite disturbance, which are akin to sickness behaviour." (PMID 33224281, 2020). "Vagus nerve stimulation has been shown to increases immune activity by elevating plasma levels of inflammatory cytokines, such as TNF-α and IL-6 in humans with depression." (PMID 32677895, 2020). "In this study, we measured serum levels of tumor necrosis factor‐α, interleukin 6, and soluble interleukin 6 receptor after major depressive disorder patients underwent antidepressant therapy." (PMID 32162496, 2020). "In a similar vein, a meta-analysis of studies measuring the IL-6 level of patients with major depression found that these levels were significantly higher than in controls." (PMID 32793188, 2020). "Based on the univariate analysis of the GLM, we found significant differences in the years of education, cytokines (IL-1β, IL-2, IL-6, IL-12p70, IL-17A, IFNγ, TNFα, IL-10, and IL-13), and depression severity (indicated by the PHQ) among the groups." (PMID 32703187, 2020). "Both EA and acupuncture can significantly decrease TNF-α and IL-6 expression, which provides antidepressant effects and improves the hippocampal neuroinflammation in animal models of depression." (PMID 33343332, 2020). "A variety of evidence implicates IL-6 in the pathogenesis of depression, and a phase 2 trial of sirukumab for patients with MDD and CRP >3 mg/L has recently completed (clinicaltrials.gov ID: NCT02473289)." (PMID 31427751, 2020). "Findings from our Mendelian randomization analyses add to the existing literature by showing that reverse causality or residual confounding are unlikely explanations for previously reported associations between IL-6, CRP and depression." (PMID 30886334, 2020). "They found selective increase of IL-6 in the cerebrospinal fluid (CSF) and a strong association between the increase of CSF IL-6 levels and the endotoxin-induced mood deterioration, suggesting that increase in the central IL-6 concentrations may contribute to depression pathogenesis." (PMID 32235786, 2020). "Similar findings were demonstrated that the depression state was positively correlated with IL-6 levels in patients with cancer, lung cancer, colorectal cancer, pancreatic cancer, breast cancer, metastatic cancer, advanced cancer and ovarian cancer." (PMID 32235786, 2020). "The results showed that serum MT, IL-6, and hcy levels in the first-episode group and recurrent group were significantly higher than those in the control group, supporting that serum MT, IL-6, and hcy levels were correlated with pathogenesis of depression." (PMID 32655450, 2020). "As observed in patients with AS, individuals with depression and anxiety have also been shown to have elevated levels of proinflammatory cytokines, including tumour necrosis factor alpha and interleukin-6." (PMID 32159073, 2020). "People who had higher serum levels of IL-6 at age nine had 1.55 higher odds of depression when they reach the age of 18 years as reported in the Avon Longitudinal Study of Parents and Children in England." (PMID 32380710, 2020). "Altered IL-6 expression alone cannot account for depressive symptom, but clinical and animal studies showed that increased IL-6 and decreased IL-10 will lead to depression." (PMID 32611425, 2020). "Among the participants with depression, TS total scores remained significantly positively correlated with log IL-6, although the correlation was stronger (r = 0.36, N = 86, p<0.01)." (PMID 32413063, 2020). "An animal study showed that long-term zeaxanthin treatment decreases the levels of IL-6, IL-1β, and TNF-α and ameliorates diabetes-associated anxiety and depression in diabetic rats." (PMID 31215856, 2020). "IFN-α induces depression by activating IL-6, which disrupts the function of tetrahydrobiopterin (BH4) in the synthesis of 5-HT." (PMID 33328856, 2020).
depression (continued). "Litratures indicate that the patients with depression usually possess high concentrations of pro-inflammatory cytokines (for instance; IL-6, and TNF-α) as compared with normal individuals." (PMID 33415126, 2020). "IL-1β and IL-6 are secreted by reactive astrocytes and can induce inflammation, and they were proven to be key factors in inducing depression." (PMID 32321532, 2020). "First, we found that the baseline levels of IL-10, IL-12p70, IL-13, IL-17A, IL-1β, IL-2, IL-23, IL-5, IL-6, IL-7, and MIP-1β were associated with depression symptoms." (PMID 32699226, 2020). "Studies have investigated peripheral IL-6 levels in different depression subtypes or their correlations with certain depressive symptoms." (PMID 32235786, 2020). "One research investigating IL6 methylation in late-life depression showed subjects with depression had lower IL6 methylation levels at one of the four sites investigated." (PMID 32235786, 2020). "Cytokines released by cell-mediated immunity, like IL-6, TNF-alpha, IL-1b, play a role in disorders like depression where these cytokines can act as risk factors or aggravate the state of depression." (PMID 33240722, 2020). "Both pancreatic cancer and major depressive disorder (MDD) have been associated with elevated levels of inflammatory cytokines, such as interleukin-6 (IL-6)." (PMID 32850269, 2020). "Meta-analyses have shown that inflammation is connected with depression, i.e., the elevated C-reactive protein, interleukin 6 (IL-6), and tumor necrosis factor alpha (TNF-α) in major depressive disorder." (PMID 32581890, 2020). "Hierarchical multiple regression analysis predicting Log IL-6 among participants with clinically significant depression Log IL-6 (N = 86)." (PMID 32413063, 2020). "A study has evaluated the relationship between depression and IL-6 and IL-10 in patients undergoing hematopoietic stem cell transplantation." (PMID 32235786, 2020). "In parallel, the associations between hopelessness and IL-6 and CRP, and between depression and CRP and MMP-9 all disappeared after adjusting for health risk behaviors." (PMID 32075162, 2020). "With meta-analysis results and many individual studies approved, depression is associated with the activation of the immune system, including increased expression of proinflammatory cytokines such as TNF-α and IL-6." (PMID 32182911, 2020). "Ingestion of these two microbes for 14 days led to depression- and anhedonia-like phenotypes, higher plasma IL-6 levels, and decreased expression of synaptic proteins in the PFC of antibiotic-treated mice." (PMID 32799901, 2020). "In this study, we detected five indicators (MT, IL-6, hcy, C3, and C4) in first-episode depression patients, recurrent depression patients, and the healthy group." (PMID 32655450, 2020). "With the important role of inflammatory processes in depression pathogenesis, among the cytokines, IL-6 has been consistently found to be elevated in stress reactions and depression patients." (PMID 32235786, 2020). "Stress is associated with higher levels of proinflammatory cytokines, such as tumor necrosis factor-α (TNF-α) and interleukin (IL)-6, in patients with depression compared with healthy individuals." (PMID 33343332, 2020). "High levels of neuro-inflammatory cytokines such as interleukin (IL)-1β, tumor necrosis factor-α (TNF-α), and IL-6 have been identified in patients with depression." (PMID 32922291, 2020). "Ingestion of these two microbes for 14 days induced depression- and anhedonia-like phenotypes, increased blood IL-6 levels, and reduced synaptic protein expression in the PFC in antibiotic-treated mice." (PMID 32799901, 2020). "Meta-analyses showed that patients with depression exhibit higher expression levels of pro-inflammatory cytokines, including interleukin-6 (IL-6) and the tumor necrosis factor-α (TNF-α), compared with healthy control subjects." (PMID 32518376, 2020).
depression (continued). "We provide evidence that, out of all cardiovascular risk factors, triglycerides and the inflammatory markers IL-6 and CRP are likely to be causally related to depression." (PMID 30886334, 2020). "NK38 and NK98 additively or synergistically suppressed depression-like behaviors, IL-6 expression in the hippocampus, and corticosterone and IL-6 levels in the blood." (PMID 32347078, 2020). "They found, compared with controls, IL-6 were significantly elevated in the aged depression subjects." (PMID 32235786, 2020). "Clinical depression is accompanied by increased pro-inflammatory cytokine interleukin (IL), such as IL-1β and IL-6." (PMID 33134190, 2020). "This study is aimed at investigating the clinical significance of changes in serum concentrations of melatonin (MT), interleukin-6 (IL-6), homocysteine (hcy), and complement C3 and C4 in depression patients and relationships of them with depression activity." (PMID 32655450, 2020). "Clinically, elevated levels of CRP and IL-6 were observed in patients with depression when compared to healthy subjects and were associated with cognitive symptoms in such patients." (PMID 32922295, 2020). "IL-6 regulates multiple pathological processes involved in depressive disorders, including the differentiation of specific T- and B-cells, acute phase response, activity of the hypothalamic-pituitary-adrenal (HPA) axis, and neuroprogression." (PMID 31215856, 2020). "The proinflammatory cytokines tumor necrosis factor-α (TNF-α) and interleukin-6 (IL-6) play critical roles in the process of inflammation and can induce depressive disorders." (PMID 32184729, 2020). "In this study, a systematic search was performed for IL-6 in depressive disorder by using the PubMed database up to September 1, 2019." (PMID 32235786, 2020). "Multiple large studies have consistently shown that there is an inverse, independent, dose–response relation between level of PA and immune cytokines (e.g., IL-6 and CRP), while depression is associated with increased plasma levels of immune cytokines." (PMID 30046989, 2019). "LPS is an effective and potent inducer of inflammatory cytokines (eg, TNF‐α; IL‐1β; IL‐6) that can acutely activate the innate immune system in the peripheral or central nervous system to induce depression‐like behaviours." (PMID 31599060, 2019). "One would expect an anti-depressive action of IL6 treatment that contrasts with sustained elevation of IL6 levels in patients with major depressive disorders and depressive-like phenotype of mice injected with recombinant IL-6." (PMID 30809118, 2019). "Studies have found that in patients with depression, IL-6 levels in the peripheral blood and cerebrospinal fluid (CSF) are higher." (PMID 31214060, 2019). "A recent study reported an enhancement of circulating pro-inflammatory cytokines (including that of IL-2, IL-6, and TNF-α), which was associated with depression in patients with CFS." (PMID 31253154, 2019). "Serum concentration of IL-6 was found to be positively correlated with Ham-D scores or the severity of depression." (PMID 30899619, 2019). "Support for IL-6 involvement in depression has also come from the many reports showing elevated levels of peripheral IL-6 in depressed patients." (PMID 30967802, 2019). "In the paroxetine study, at randomisation we observed a positive correlation between IL-6 (r = 0.23, p = 0.018) and IL-10 (r = 0.19, p = 0.045) levels and severity of depression evaluated by HAMD." (PMID 31375659, 2019). "In apparent contradiction to these results is the observation that rats which are resilient to learned helplessness (a further rodent model of depression) have lower brain levels of IL-6 than their helpless counterparts." (PMID 31362361, 2019). "Serum IL-6 and sIL6R have also been found to be higher after delivery, especially in women with a history of depression." (PMID 31362361, 2019).
depression (continued). "Compared with HCs (n=30), patients with SLE (n=36) scored higher on measures of depression, fatigue and had higher hsCRP (p=0.013), IL-6 (p=0.003) and B lymphocyte stimulator (p<0.001)." (PMID 30979715, 2019). "Administration of IL-6 induced depression in mice, and this outcome was prevented by pharmaceutical blockage of NE neurons in the brainstem." (PMID 32009871, 2019). "Database STRING showed statistically significant associations of the human genes homologous to these rat genes with long-term depression, circadian entrainment, Alzheimer’s disease, and the central nervous system disorders during chronic IL-6 overexpression." (PMID 31921305, 2019). "Another independent study in major depression also showed that LPS-induced monocytes from patients with depression secreted lower levels of IL-1β, IL-6, and TNFα than those from the control group." (PMID 31152269, 2019). "Increasing evidence points to a pro-inflammatory state in patients with unipolar depression (increased serum interleukin (IL)-6) and bipolar depression (increased levels of IL-1, IL-6 and TNF-alpha)." (PMID 31671812, 2019). "Inflammatory factors were reported to be associated with depression; as such, we tested the expression of IL-1β and IL-6 in serum samples of 30 normal donors (ND), 30 GC patients, and 30 GC patients with depression." (PMID 31396300, 2019). "This study aimed to examine the serum levels of interleukin-6 (IL-6) and C-reactive protein (CRP) in MDD patients to find out their association with depression." (PMID 30899619, 2019). "Studies have found that people with major depression have higher levels of pro-inflammatory cytokines, for example, IL-1, IL-6, and tumor necrosis factor-alpha, and C-reactive protein." (PMID 31214060, 2019). "C-reactive protein (CRP) and Interleukin 6 (IL-6) are common inflammatory markers, and elevated levels of CRP and IL-6 are associated with increased risk for psychological distress and depression." (PMID 32009956, 2019). "Depression is closely associated with altered inflammation, manifested by increased expression of inflammatory cytokines such as TNF-α and IL-6." (PMID 31672153, 2019). "IL-6 is correlated with the prognosis and depression of cancer patients and is considered to the therapy target." (PMID 31645619, 2019). "For instance, depressed patients with metabolic syndrome or patients suffering from atypical depression (e.g., hyperphagia, weight gain, hypersomnia) display high plasma levels of IL-6." (PMID 31362361, 2019). "Patients with depression exhibited an upregulation of proinflammatory cytokines, including interleukin-1β (IL-1β), IL-6, and tumor necrosis factor-α (TNF-α)." (PMID 32009949, 2019). "High IL-6 levels are directly related to rheumatoid arthritis, diabetes, depression, and myeloma, leading to a medical interest in controlling IL-6 activity, since it can act in tumor cell growth." (PMID 30608959, 2019). "Specifically, patients with treatment resistant depression display elevated levels of inflammatory cytokines and chemokines such as interleukin 6 (IL6) and monocyte chemoattractant protein 1 (MCP-1)." (PMID 31827434, 2019). "The three anti-TNF-a drugs and the anti-IL-6 antibody (tocilizumab) significantly improved symptoms of depression." (PMID 31214060, 2019). "These kinds of interference are frequently made in studies assessing CRP and IL-6 in relationship to stress or depression and that conclude as to the role of inflammation in these conditions." (PMID 30769887, 2019). "Chronic stress, a precipitant of depression, exacerbates age-related increases in inflammatory responses and increases circulating IL-1β and IL-6 and cognitive impairment in elderly patients." (PMID 31383842, 2019). "Increased inflammatory blood markers (e.g., CRP and IL-6) correlated with greater overall symptom severity in patients with depression, in particular with neuro-vegetative symptoms (e.g., sleep, appetite)." (PMID 30116031, 2019).
depression (continued). "A longitudinal study showed that people with higher IL-6 at age nine are more likely to have depression at age 18 in a dose dependent manner, even adjusting for a variety of factors." (PMID 31379879, 2019). "Using Mendelian randomisation analysis of the UK Biobank sample, we previously found that out of all cardiovascular risk factors, IL-6, CRP and triglycerides are likely to be causally linked with depression." (PMID 31258105, 2019). "Using longitudinal data from a general population-representative birth cohort, we have examined associations between childhood IL-6 and CRP levels and specific symptoms of depression in early adulthood." (PMID 30414442, 2019). "IL-6 and IL-4 were the main contributing cytokines for prediction of the geriatric depression scale, and all the top cytokine variables also contributed to the prediction of the Schwab and England ADL scale." (PMID 31372494, 2019). "It was found that GTS treatment can alleviate depression‐like behaviour impairments and decrease mRNA levels of IL‐1b, IL‐6, TNF‐a and IDO in the hippocampus." (PMID 31599060, 2019). "Zinc has been shown to influence brain-derived neurotrophic factor (BDNF) activities, which were found to be related to depression, and to affect depression by reducing several makers of inflammation, such as C-reactive protein or interleukin-6." (PMID 30781841, 2019). "Symptoms of depression are often caused by pro-inflammatory cytokines, mainly due to tumor necrosis factor α (TNF-α), interleukin 1 beta (IL-1β), and interleukin 6 (IL-6)." (PMID 31771312, 2019). "It has been reported that circulating IL-6 and TNF-α levels were significantly linked to patients with the severity of anxiety, depression and cognitive impairment." (PMID 31213027, 2019). "IL-6 signaling can result from activation of inflammatory pathways and alterations in IL-6 levels in the brain were demonstrated contributing to depression symptomatology." (PMID 31849598, 2019). "Increases in serum pro- and anti-inflammatory cytokines have been observed in patients with depression, such as IL-1β, IL-6, and TNF-α, and IL-10, respectively." (PMID 30678337, 2019). "In the first mechanism, DHA and EPA can lead to decrease in production of proinflammatory cytokines, such as tumor necrosis factor (TNF)-α42, interleukin (IL)-1β, IL-2, and IL-6, which are determined by eicosanoid discharge and related to depression." (PMID 31383846, 2019). "Patients with depression frequently exhibit increased levels of C-reactive protein, tumor necrosis factor-alpha, and interleukin-6 (Miller, Maletic & Raison, 2009)." (PMID 31592197, 2019). "In a more recent, larger scale meta-analysis a greater range of changes have been described in people with depression, including higher levels of TNFα, IL-6, IL-13, IL-18, IL-12, IL-1RA, and sTNFR2, along with a decrease in the proinflammatory cytokine IFNγ." (PMID 31379879, 2019). "One study testing the efficacy and safety of sirukumab (anti-IL-6 mAb) for depression has completed recruitment (NCT02473289)." (PMID 31258105, 2019). "Subgroup analysis indicated elevated serum IL-6 in both the depression and manic phases in BD patients." (PMID 30762747, 2019). "Further analysis of this study population found that levels of pro-inflammatory cytokines, including IL-6 and IL-18, predicted subsequent depression in patients with ACS." (PMID 30890971, 2019). "In a chronic mild stress (CMS) model of depression, higher concentrations of IL-1β and IL-6 in the brain and IL-6 and TNF-α in serum were shown." (PMID 30610610, 2019). "A recent cumulative meta-analysis confirmed the robust nature of the depression–inflammation relationship, showing evidence of increased circulating interleukin-6 and C-reactive protein (CRP) in depressed compared with non-depressed individuals." (PMID 30220259, 2019). "Supporting evidence was also provided by the finding that in depression, serum levels of IL-6 predict patients’ response to ketamine." (PMID 31214060, 2019).